IFNE (interferon epsilon)
Description:
Type I interferon required for maintaining basal levels of IFN-regulated genes, including 2'-5'-oligoadenylate synthetase, IRF7 and ISG15, in the female reproductive tract. Directly mediates protection against viral and bacterial genital infections (By similarity).
Synonyms: IFNE1; IFN-E; IFNT1; INFE1; PRO655
Tractability: Antibody: UniProt places it where antibodies can reach, with high confidence; UniProt predicts a signal peptide or a membrane-spanning region; its Gene Ontology location is reachable by antibodies, with medium confidence.
Gene: Protein-coding gene on chromosome 9 (21,480,839 to 21,482,313, reverse strand). Ensembl gene ENSG00000184995.
Subcellular location: Secreted
Gene Ontology:
Molecular function: cytokine activity; type I interferon receptor binding; cytokine receptor binding
Biological process: adaptive immune response; B cell activation involved in immune response; cellular response to virus; defense response to bacterium; defense response to virus; humoral immune response; natural killer cell activation involved in immune response; response to exogenous dsRNA; T cell activation involved in immune response; type I interferon-mediated signaling pathway; defense response
Cellular component: extracellular region
Genetic constraint (gnomAD): Loss-of-function variants: 0 observed, 0.0819 expected, observed/expected ratio (o/e) 0, 90% interval 0 to 1.89. That is too few expected variants to judge how well the gene tolerates losing a copy. Missense variants: 276 observed, 245.82 expected, observed/expected ratio (o/e) 1.12, 90% interval 1.02 to 1.24. Synonymous variants: 94 observed, 93.15 expected, observed/expected ratio (o/e) 1.01, 90% interval 0.85 to 1.2.
Homologues: Orthologues: chimpanzee IFNE (99% identical), pig IFNE (71% identical), rabbit IFNE (62% identical), rat Ifne (54% identical), mouse Ifne (54% identical), tropical clawed frog ifn4 (18% identical), zebrafish ifnphi3 (18% identical), zebrafish ifnphi2 (15% identical). Paralogues in human: IFNA1 (32% identical), IFNA13 (31% identical), IFNA21 (31% identical), IFNA5 (31% identical), IFNA14 (31% identical), IFNA17 (31% identical), IFNA7 (31% identical), IFNA10 (30% identical), IFNA16 (30% identical), IFNA2 (30% identical), IFNB1 (30% identical), IFNA4 (30% identical), and 4 more.
Diseases named in the same sentence as IFNE in open-access papers:
IFNE is named in the same sentence as 42 diseases in open-access papers, as found by Europe PMC text mining. Sharing a sentence is not in itself a finding about the gene and the disease. The quoted sentences say what the papers report.
viral infections (22 papers, 2013 to 2025). "Overall, this study indicates that endogenous production of IFNε by the testis plays an essential role in anti-viral defence by limiting the consequences of virus infection in an organ that is relatively deficient in inducible anti-viral defences." (PMID 39621805, 2024). "Clearly, it will be important to assess whether differences in IFNε regulation or activity contributes to the susceptibility to viral infection, persistence and severity of orchitis in human patients." (PMID 39621805, 2024). "It is thus possible that expression of these IFNs may offset the observed significant decrease in placental IFNE associated with viral infection of the fetus and, thereby, play a vital role in mediating fetal resilience at the placenta." (PMID 33148169, 2020). "Exogenous IFNε treatment reduced the viral infection burden in cultured human testicular cells by inducing interferon-stimulated gene expression, and reducing inflammatory gene expression and cell damage." (PMID 39621805, 2024). "Other important members of the type I IFN family (IFNε, IFNκ) were already characterized during viral infections like HSV-1/2, Zika virus or human papillomavirus (HPV) in the vaginal tract or in HSV-1-infected keratinocytes." (PMID 36325470, 2022). "Despite the antagonistic mechanisms that target conventional type I IFNs (IFN α and β), various cell types express other type I IFNs that confer innate protection against viral infections, including interferon epsilon (IFNε)." (PMID 36014974, 2022). "We included IFNε because it is unique among IFNs as, in mice, the expression is regulated hormonally instead of induced by viral infection." (PMID 32109259, 2020). "While the in vitro anti-viral activity of IFNε is weaker than that of IFNα, IFNε efficiently clears viral infections in vivo by recruiting lymphocytes and by increasing the numbers and functions of cytotoxic T cell subsets in mucosal tissues." (PMID 29118969, 2017). "Additionally, we characterised the constitutive nature of IFNε expression with respect to virus infection and showed that in contrast to type-I and III IFNs, endogenous expression of IFNε was not susceptible to ZIKV-mediated evasion." (PMID 36897927, 2023). "IFNε treatment inhibited viral infection of both Ect1 and VK2 cells by ~90%, whether determined by plaque assay or viral RNA (Ect1 vRNA: 88% reduced)." (PMID 36897927, 2023). "To understand the importance of IFNε’s constitutive expression on ZIKV evasion of IFN responses in humans, compared to IFN expression that is induced following viral infection, we treated the placental trophoblast cell line HTR8, with IFNε or IFNα either pre- or post-infection with ZIKV." (PMID 36897927, 2023). "Our findings demonstrating direct, IL-15-independent effects of IFNε on NK cells are consistent with reports that NK cell expression of the type I IFN receptor (IFNAR) is required to mediate their cytolytic activity and IFNγ production in other sites during viral infections." (PMID 38263527, 2024). "IFNε is unique compared to other canonical type-I IFNs in that it is constitutively expressed by epithelial cells of the FRT with expression levels controlled by progesterone and not in response to viral infection." (PMID 36897927, 2023).
COVID-19 (9 papers, 2021 to 2023). A disease caused by infection with severe acute respiratory syndrome coronavirus 2. "Gene expression in PBCs of interferon epsilon (IFNE) exhibited sex-specific differences, and therefore it was analyzed according to COVID-19 severity and obesity independently in the two sexes." (PMID 36009555, 2022). "Anti-cytokine autoantibodies (e.g., antibodies against IFNα, IFNε, IL-6, IL-22, GM-CSF and TNFα) may also provide a potential target for COVID-19 treatment." (PMID 36341384, 2022). "Interestingly, the expression pattern of ADAM17, IFITM3 and IFNE in PBCs was related to both the severity of COVID-19 evolution and obesity status, especially in the male patients." (PMID 36009555, 2022). "A robust type I IFN response in severe COVID-19 patients has been described, which could exacerbate hyperinflammation through diverse mechanisms, but the induction of IFNE specifically and the radical differences depending on sex were unknown." (PMID 36009555, 2022). "IFNE expression in PBC was higher in female than male control subjects and was increased by COVID-19 in the male patients only, to an extent that was related to both the severity course of the disease and the BMI range." (PMID 36009555, 2022). "IFN genes IFNG and IFNE, and IFN receptors IFNAR2 and IFNGR2, were upregulated in COVID-19 vs non-COVID19, suggesting a crucial role for IFN-signaling in mounting an anti-SARS-Cov-2 response." (PMID 33473155, 2021). "Higher basal type 1 IFNs expression, including IFNE, may allow females to maintain a high T-cell level in the early stages of SARS-CoV-2 infection, leading to a milder evolution of COVID-19." (PMID 36009555, 2022). "Thus, from the data herein, it can be proposed that the levels of expression of IFNE, as measured in PBCs, can be useful to predict different levels of severity outcome of COVID-19 in male patients, but not females." (PMID 36009555, 2022).
cervical cancer (5 papers, 2013 to 2023). A primary or metastatic malignant neoplasm involving the cervix. "Matsumiya and colleagues demonstrated that TNFα at a concentration of 10 ng/ml or higher induces IFNε mRNA expression by near twofold in HeLa cells, a cervical cancer cell line, although TNFα did not induce the IFNε promoter activity in this study." (PMID 29118969, 2017). "The upregulation of STAT1 mediated by interferon epsilon (IFNE) was described on cervical cancer cells, but to our knowledge, there are no studies describing the role of IFNE in CC." (PMID 23865481, 2013).
ZIKV infection (5 papers, 2019 to 2024). "This reduction in IFNε may contribute to the natural susceptibility of WT mice during diestrus and pregnancy to iVag ZIKV infection compared to systemic inoculation methods." (PMID 36897927, 2023). "To assess the role of endogenous IFNε in testicular antiviral defence in mice, we used a murine model of systemic Zika virus infection." (PMID 39621805, 2024). "In this work we investigate the role of a hormonally regulated type I interferon, IFN epsilon (IFNε) in control of Zika virus (ZIKV) infection of the FRT." (PMID 36897927, 2023). "In this study we demonstrate the importance of IFNε as a major effector in resistance of the FRT to ZIKV infection." (PMID 36897927, 2023). "Together, this data demonstrates endogenous IFNε expression in the FRT has a significant impact on local ZIKV infection and viral dissemination at early times post infection by the nature of its constitutive expression prior to infection." (PMID 36897927, 2023). "In apparent contrast to our observations that indicate IFNε plays a significant role in protecting the FRT from ZIKV infection, multiple groups have observed type-I and III IFN independent protection of the FRT during estrus in mice." (PMID 36897927, 2023). "Having demonstrated that IFNε plays an important role in control of ZIKV infection in mice it was important to determine the effect and mechanism of action in human cells." (PMID 36897927, 2023). "We then evaluated the impact of recombinant IFNε on ZIKV infection in these cells, compared to other IFNs that are important modulators of antiviral activity at mucosal surfaces (IFNα and IFNλ-III)." (PMID 36897927, 2023). "We aimed to further characterize the antiviral effects of IFNε on ZIKV infection of hVECs under pre-treatment and post-treatment conditions." (PMID 36014974, 2022). "Considering ZIKV as a sexually transmitted flavivirus, it is important to examine the antiviral role of IFNε during ZIKV infection in human vaginal epithelial cells." (PMID 36014974, 2022). "In conclusion, this study shows that constitutive IFNε expression in the testis is a crucial antiviral defence mechanism in the male reproductive tract and its absence leads to inflammation induced damage to male fertility following Zika virus infection." (PMID 39621805, 2024). "In the absence of IFNε, mice were more susceptible to ZIKV infection in tissues of the reproductive tract with higher viral titres in vaginal washes (VW) 2, 5 and 7 days post-infection (dpi)." (PMID 36897927, 2023). "ZIKV infection via iVag inoculation was compared between WT, IFNε-/- and IFNAR1-/- mice." (PMID 36897927, 2023). "To determine the contribution of endogenous IFNε expression in the FRT, relative to other (conventional) type-I IFNs to prevent ZIKV infection, we compared the outcomes of intravaginal (iVag) infection of wildtype (WT), IFNε-/- or IFNAR1-/- mice with 5 X 105 FFU of ZIKV Puerto Rican stain PRVABC59." (PMID 36897927, 2023). "Similarly, VK2E6E7 cells treated with IFNε showed reductions in overall ZIKV infection under post-treatment conditions." (PMID 36014974, 2022). "This inverse relationship further validated the antiviral effects of IFNε during ZIKV infection." (PMID 36014974, 2022). "However, this assumes infection cannot inhibit IFNɛ expression, therefore we asked if ZIKV infection could antagonise the expression of IFNε." (PMID 36897927, 2023). "This demonstrates for ZIKV infections, the FRT can be pre-emptively tuned to an antiviral state and that it appears to be a unique property of IFNε, stemming from the different regulatory pathways that govern its expression." (PMID 36897927, 2023). "Pre-treatment with either IFNε, IFNα or IFNλ3 protected Ect1 and VK2 cells from ZIKV infection, indicating the importance of both type-I and III IFNs in protection of the FRT in humans." (PMID 36897927, 2023).
ZIKV infection (continued). "HeLa cells are known to express IFNε RNA at levels similar to FRT cell lines, therefore we used these to investigate expression of IFNε compared to other type-I and III IFNs in response to ZIKV infection or poly I:C stimulation (viral mimic)." (PMID 36897927, 2023). "Comparatively we demonstrate that IFNε expressed in the UFRT, the site of in utero transmission, is essential for ZIKV infection control." (PMID 36897927, 2023). "Here we demonstrate the non-redundant role of a relatively uncharacterised type-I IFN; IFNε, in protecting the FRT from ZIKV infections both in vitro and in a mouse model of vaginal infection." (PMID 36897927, 2023). "This also suggests that at times when IFNε is reduced, such as early pregnancy, the FRT is likely more vulnerable to ZIKV infection." (PMID 36897927, 2023). "Significantly, we discovered that the lack of IFNε exacerbates the severity of Zika virus infection in mice leading to orchitis and epididymal fibrosis." (PMID 39621805, 2024). "We found that IFNε generated antiviral responses in FRT Ect1 and VK2 cell lines by inducing a typical IFN antiviral signature, including upregulation of several ISGs known to inhibit ZIKV infection." (PMID 36897927, 2023). "Consistent with previous reports, IFNε was not significantly induced in response to either ZIKV infection or poly I:C transfection." (PMID 36897927, 2023). "Together this data demonstrates IFNε constitutive expression is not altered following ZIKV infection." (PMID 36897927, 2023).
melanoma (2 papers, 2013 to 2025). A malignant, usually aggressive tumor composed of atypical, neoplastic melanocytes. "The rs751173 polymorphism located in an intergenic region between the interferon, epsilon (IFNE) and the MTAP genes showed association with a statistical significant increased melanoma risk." (PMID 23816148, 2013).
vaginal infection (2 papers, 2013 to 2023). "To assess the contribution of endogenous IFNε in controlling ZIKV FRT infections we used a murine model of vaginal infection." (PMID 36897927, 2023).
Achalasia (1 paper, 2022). A disorder of esophageal motility characterized by the inability of the lower esophageal sphincter to relax during swallowing and by inadequate or lacking peristalsis in the lower half of the body of the esophagus. "The function of IFNε, and its impact on intraepithelial leukocyte activation in the esophagus and in achalasia is yet to be determined." (PMID 36450816, 2022). "We also observed that achalasia patients had a strong increase in mRNA expression levels of the type I interferon IFNε, in both the distal and proximal esophageal mucosa compared to controls." (PMID 36450816, 2022).
Azoospermia (1 paper, 2024). Absence of any measurable level of sperm,whereby spermatozoa cannot be observed even after centrifugation of the semen pellet. "Testicular biopsies with intact spermatogenesis obtained from infertile men suffering obstructive azoospermia were examined for IFNε expression." (PMID 39621805, 2024).
breast carcinoma (1 paper, 2019). "The study then assesses the cytotoxicity of IFNε against two human breast cancer cell lines MDA-MB-231 and MCF-7." (PMID 31490936, 2019). "We examined the effect of IFNε on two breast cancer cell lines MDA-MB-231 and MCF-7." (PMID 31490936, 2019).
Chlamydia infection (1 paper, 2024). "We used intracellular cytokine staining and flow cytometry to determine the effects of IFNε deficiency on NK cell number, phenotype, activation, and IFNγ production during Chlamydia infection in the FRT following the gating strategy shown in Fig. EV1D–F." (PMID 38263527, 2024). "We show that the constitutive expression of IFNε in the uterus plays a crucial role in promoting the accumulation, activation, and IFNγ production of NK cells in uterine tissue during Chlamydia infection." (PMID 38263527, 2024). "Since previous studies also showed 3dpi to be the peak of NK cell infiltration in this model of Chlamydia infection, we focused on this time point to further characterize the effects of IFNε on NK cell responses." (PMID 38263527, 2024). "We show that IFNε promotes NK cell accumulation, activation, and effector cytokine production in response to Chlamydia infection through IL-15-dependent and -independent mechanisms." (PMID 38263527, 2024). "In this study, we show that IFNε is responsible for promoting the infiltration, activation, and IFNγ production of NK cells in the uterus during Chlamydia infection." (PMID 38263527, 2024). "Since NK cells can influence T cell polarity and T cells are another source of IFNγ during Chlamydia infection, we also assessed the effect of IFNε on IFNγ production by T cells during infection." (PMID 38263527, 2024).
chlamydial infection (1 paper, 2022). "Lastly, we examined secretion of IFNε from WT (C57Bl/6) or ERKO mice during mock or chlamydial infection." (PMID 36636722, 2022). "Additionally, these data indicate that DMPA differenitally regulates expression of IFNε during chlamydial infection compared to naturally occuring sex hormones in BALB/c mice." (PMID 36636722, 2022).
colorectal cancer (1 paper, 2021). A primary or metastatic malignant neoplasm that affects the colon or rectum. "IFNE has been identified as an apoptosis regulatory gene that can suppress cell proliferation in human colorectal cancer cells, despite its role in protecting the female reproductive tract against viral and bacterial infection." (PMID 34573430, 2021).
gastric cancer (1 paper, 2025). A primary or metastatic malignant neoplasm involving the stomach. "This aligns with emerging evidence that elf3 directly binds to the IRF6 promoter in a human gastric cancer cell line and to the interferon epsilon promoter in HEK293 cells." (PMID 41147741, 2025).
haemorrhage (1 paper, 2023). "Interestingly, one study in humans has linked a polymorphism of IFNε to cerebral haemorrhage, indicating it may be functionally expressed in this tissue." (PMID 36897927, 2023).
liver fibrosis (1 paper, 2016). "The association of other transcripts such as CD70, IFNE and IRF3 with liver fibrosis has been scarcely reported." (PMID 27135246, 2016).
Obesity (1 paper, 2022). Accumulation of substantial excess body fat. "Thus, expression patterns of three genes (IFITM3, ADAM17, IFNE) in PBCs at the time of hospital admission marked both disease evolution severity and obesity status, especially in male patients." (PMID 36009555, 2022). "ADAM17, IFITM3, IL6 and IFNE were more highly expressed in PBCs of patients with obesity." (PMID 36009555, 2022).
ovarian carcinoma (1 paper, 2024). A malignant neoplasm originating from the surface ovarian epithelium. "Notably, interferon epsilon (IFN-ε), a recently discovered member of the IFN-I family, has been identified as an intrinsic suppressor of ovarian cancer." (PMID 39034318, 2024).
sexually (1 paper, 2022). "Interestingly, IFNE is unusual among type I IFNs in that it is primarily constitutively expressed in the mucosal epithelium of the female reproductive tract, where it is hormonally regulated by sex hormones and it confers protection against sexually transmitted viral and bacterial infections." (PMID 36009555, 2022).
sexually transmitted infections (1 paper, 2023). "The role of interferon epsilon (IFN‐ε) in human sexually transmitted infections, particularly human papillomavirus (HPV), remains poorly understood." (PMID 38156399, 2023).
uterine infection (1 paper, 2023). "During the luteal phase of the estrus cycle, IFNE is highly expressed in the uterus and has a protective effect against uterine infection." (PMID 37113996, 2023).